EGF (epidermal growth factor)
Diseases named in the same sentence as EGF in open-access papers (continued):
Sharing a sentence is not in itself a finding about the gene and the disease.
Familial adenomatous polyposis (1 paper, 2021). Familial adenomatous polyposis (FAP) is characterized by the development of hundreds to thousands of adenomas in the rectum and colon during the second decade of life. "In familial adenomatous polyposis (FAP), chemoprevention strategies using combined cyclo-oxygenase and epidermal growth factor inhibitors show promise in clinical trials, but they are not in routine clinical use." (PMID 33822054, 2021).
familial hypercholesterolemia (1 paper, 2016). An inheritable form of hyperlipidemia, in which there are excess lipids in the blood. "Transport of ER-derived cholesterol to MVBs ensures that EGF-stimulated ILV formation proceeds to completion, even when LDL-cholesterol in the endocytic pathway is low, as found for example in cells from familial hypercholesterolemia patients carrying mutations that prevent LDL uptake." (PMID 27270042, 2016).
Fibroadenoma (1 paper, 2018). A benign tumor of the breast characterized by the presence of stromal and epithelial elements. "We also observed increased levels of FGF2 and EGF in fibroadenomas (data not shown)." (PMID 30019538, 2018).
fibrolamellar hepatocellular carcinoma (1 paper, 2022). A distinctive type of liver cell carcinoma that arises in non-cirrhotic livers and is seen predominantly in young patients. "NT also seems to act as a co-mitogenic factor in the presence of its receptor NTSR1 and epidermal growth factor (EGF) in tumor slice cultures of fibrolamellar hepatocellular carcinoma." (PMID 35216326, 2022).
focal segmental glomerulosclerosis (1 paper, 2022). A renal disorder characterized by sclerotic lesions in the glomeruli. "It was found that fibronectin 1 (FN1), epidermal growth factor (EGF), and transthyretin (TTR) showed considerable diagnostic efficiency for focal segmental glomerulosclerosis, which was based on bioinformatics analysis." (PMID 36199375, 2022).
gastrointestinal stromal tumor (1 paper, 2012). "Gastrointestinal stromal tumors express several EGFR ligands, but not EGF." (PMID 22209887, 2012).
Giardia infection (1 paper, 2022). "The Giardia infection disruption of intestinal epithelial TJ proteins (i.e., ZO-1) was strain-dependent and could be reversed by using caspase-3 inhibitors or the pre-treatment with the epidermal growth factor (EGF)." (PMID 35250996, 2022).
gram-negative bacterial infections (1 paper, 2015). Infections caused by bacteria that show up as pink (negative) when treated by the gram-staining method. "MMP9, for example processes epidermal growth factor (EGF) precursors into active EGF receptor ligands thereby co-amplifying inflammation in Gram negative bacterial infection." (PMID 25615645, 2015).
hemangioma (1 paper, 2021). A benign vascular lesion characterized by the formation of capillary-sized or cavernous vascular channels. "Many RTK growth factors, such as VEGF, PDGF, FGF2, and EGF, have been demonstrated in the pathogenesis of hemangioma." (PMID 33400686, 2021).
hemochromatosis (1 paper, 2025). A disorder of iron metabolism characterized by a triad of HEMOSIDEROSIS; LIVER CIRRHOSIS; and DIABETES MELLITUS. "The hepatocyte Smad1/5/8 knockout murine model of hemochromatosis revealed an important role of SMAD8 in hepcidin regulation and demonstrated that testosterone and epidermal growth factor (EGF) require SMAD1/5/8 to regulate hepcidin production." (PMID 40149659, 2025).
hemophilia A (1 paper, 2023). The most common form of hemophilia characterized by spontaneous or prolonged hemorrhages due to factor VIII deficiency. "Four years later, in 2018, emicizumab (HemlibraTM), which targets clotting factors IXa and X, was approved for hemophilia A. Finally, in 2021, amivantamab-vmjw (RybrevantTM), which targets epidermal growth factor and MET receptors, received authorization for the treatment of cancer." (PMID 36770706, 2023).
Hereditary breast cancer (1 paper, 2019). Breast carcinoma that has developed in relatives of patients with history of breast carcinoma.
Hodgkins lymphoma (1 paper, 2017). A heterogeneous group of malignant lymphoid neoplasms of B-cell origin characterized histologically by the presence of Hodgkin and Reed-Sternberg (HRS) cells in the vast majority of cases. "For example, EGF-MAP achieved a half-maximal inhibitory concentration (IC50) of 1 μM against pancreatic L3.6pI cells, and Ki(scFv)-MAP achieved an IC50 value of 53 nM against the Hodgkin’s lymphoma cell line L540cy." (PMID 28704435, 2017).
hyperopia (1 paper, 2021). A refractive error in which rays of light entering the eye parallel to the optic axis are brought to a focus behind the retina, as a result of the eyeball being too short from front to back. "The findings may weakly suggest a co-incidence of axial hyperopia and AMD in association with a relative lack of EGF." (PMID 33713254, 2021).
hyperphosphatemia (1 paper, 2021). Abnormally high level of phosphate in the blood. "Previous studies had shown that in some disease states, such as hyperphosphatemia induced by intestinal ischemia/injury, serum Pi levels and EGF levels were increased, which indicated that EGF might play a role in regulation of Pi homeostasis in response to intestinal injury." (PMID 34195248, 2021).
hyperprolactinemia (1 paper, 2021). Abnormally high level of prolactin in the blood. "Hyperprolactinemia likely results from functional disruption of the physiological dopaminergic inhibition, although direct stimulation by EGF, which is abundantly produced by SG, may be hypothesized." (PMID 33939106, 2021).
hyperthyroidism (1 paper, 2023). Overactivity of the thyroid gland resulting in overproduction of thyroid hormone and increased metabolic rate. "Pro-Epidermal Growth Factor (EGF) is an essential growth factor in thyroid tissue, and nuclear EGFR expression is elevated in GD tissue samples, implying that the EGFR-dependent modulation of thyroid cell proliferation under physiological conditions may be associated with hyperthyroidism." (PMID 37859983, 2023).
infantile hemangioma (1 paper, 2021). "Our findings suggest that NGBR was a promising therapeutic target for attenuating RAS signaling in infantile hemangioma induced by concurrent RTK growth factors, such as EGF, FGF2, and VEGF." (PMID 33400686, 2021).
Inguinal hernia (1 paper, 2013). Protrusion of the contents of the abdominal cavity through the inguinal canal. "He underwent inguinal hernia surgery (major surgery) thirty-two months after starting CIMAvax® EGF treatment for NSCLC." (PMID 24127898, 2013).
Intellectual disability (1 paper, 2017). "One mutation in the epidermal growth factor gene (EGF) has been associated with a recessive form of hypomagnesemia with an additional neurological phenotype (including intellectual disability)." (PMID 27234911, 2017).
interstitial cystitis (1 paper, 2005). A rare chronic debilitating urogenital disease characterized by urinary frequency, urgency, and pelvic pain. "However, APF, HB-EGF, and EGF were the most sensitive and specific for IC, with anti-proliferative factor activity most clearly separating the interstitial cystitis and control groups." (PMID 15862132, 2005).
intestinal inflammation (1 paper, 2017). "By promoting the secretion of thymic stromal lymphopoietin, epidermal growth factor, IL-10, IL-25, and transforming growth factor-β1 by intestinal epithelial cells, Gal1 can inhibit experimental intestinal inflammation." (PMID 28086216, 2017).
intestinal tumor (1 paper, 2017). "Serum and EGF-starved HC11 cells cultured for 24 h with BKM120 revealed upregulation of Erbb3 mRNA, consistent with previous observations that PI3K inhibition causes increased Erbb3 gene expression in breast, lung, and intestinal tumor cells." (PMID 28886748, 2017).
ischemia reperfusion injury (1 paper, 2017). Adverse functional, metabolic, or structural changes in ischemic tissues resulting from the restoration of blood flow to the tissue (reperfusion), including swelling; hemorrhage; necrosis; and damage from free radicals. "EGF application in the mucosa can promote intestinal proliferation and improve restoration after intestinal injury, and it might be an effective treatment against intestinal ischemia-reperfusion injury in rats." (PMID 28558652, 2017).
keratosis (1 paper, 2021). A skin disorder consisting of hypertrophy of the stratum corneum of the skin. "On days 6, 9 and 12, the CCN and EGF@CCN groups showed significantly fewer inflammatory cells, a more regular arrangement of collagen fibers, and more obvious epithelial hyperplasia keratosis than the control group." (PMID 33738123, 2021).
kidney injury (1 paper, 2015). Trauma to the kidney. "It is well recognized that MSCs can secrete a broad range of trophic factors, such as HGF, bFGF, IGF-1, and EGF, all known to improve the renal function in animal models of kidney injury, due to their antiapoptotic, mitogenic, and morphogenic activities on intrarenal cells." (PMID 26167475, 2015).
kidney tumors (1 paper, 2021). "Inhibition of EGF signaling has been shown to decrease in vitro growth of TSC-associated lung and kidney tumors." (PMID 33445520, 2021).
Kindler syndrome (1 paper, 2019). Kindler syndrome (KS) is the fourth major type of epidermolysis bullosa (EB), besides simplex, junctional and dystrophic forms, and is characterized by skin fragility and blistering at birth followed by development of photosensitivity and progressive poikilodermatous skin changes. "In this study we show that skin and keratinocytes from Kindler syndrome patients have significantly reduced expression levels of the EGFR, resulting in defective EGF-dependent signaling and cell migration." (PMID 30248333, 2019).
latent infection (1 paper, 2020). "The detection of miR-US5-2 during latent infection suggests that the miRNA may modulate the EGFR signaling stimulated by UL138, perhaps as a mechanism to fine-tune the responses induced by exogenous EGF." (PMID 32759334, 2020).
Legius syndrome (1 paper, 2020). Legius syndrome, also known as NF1-like syndrome, is a rare, genetic skin pigmentation disorder characterized by multiple cafC)-au-lait macules with or without axillary or inguinal freckling. "We have previously demonstrated that SPRED1 overexpression decreased RAS-GTP following EGF stimulation in HEK293T cells and that SPRED1 mutants found in Legius syndrome were unable to decrease RAS-GTP." (PMID 32697994, 2020).
leprosy (1 paper, 2025). Leprosy is a chronic infectious disease affecting primarily the skin and peripheral nervous system. "In this line, several studies have established the application of topical EGF in accelerating the healing time in chronic wounds, such as venous, arterial, and diabetic ulcers, burns, and infected wounds like leprosy." (PMID 39808642, 2025).
lichen sclerosus (1 paper, 2019). "Serpin A1 expression is enhanced by the cytokines EGF, TNF-α, INF-γ, and IL-1β in cutaneous SCC cells and the latter three are also upregulated in lichen sclerosus." (PMID 30607583, 2019).
liver failure (1 paper, 2020). A liver disease characterized by the liver losing or has lost all of its function. "IL-6 and EGF are key to liver regeneration, and mice defective in IL-6 were reported to develop post-hepatectomy liver failure." (PMID 32443494, 2020).
lung tumour (1 paper, 2021). "In contradiction to our results, lung tumour patients showed a significant association of serum EGF with sex (p = 0.004) and smoking status (p = 0.011)." (PMID 34115785, 2021). "In our study, EGF had a low accuracy (AUC = 0.606) as a predictive marker for the sensitivity of therapy with platinum derivatives within the lung tumour population and the head and neck tumour population." (PMID 34115785, 2021). "In this study, serum epidermal growth factor (EGF) as a biomarker in patients with head and neck tumours and lung tumours, was investigated." (PMID 34115785, 2021). "In this study, we investigated serum epidermal growth factor (EGF) in an oncological population of head- and neck and pulmonary neoplasms and whether serum EGF could serve as a prognostic marker of survival and as a predictive marker for treatment response to platinum-based chemotherapy." (PMID 34115785, 2021).
macrosomia (1 paper, 2010). "A perusal of our observations suggests that human GDM and macrosomia are associated with down-regulation of GH and up-regulation of several growth factors, principally IGF-I, EGF, FGF-2 and PDGF-B." (PMID 20144210, 2010).
macular degeneration (1 paper, 2019). Loss of vision in the central portion of the retina (macula), secondary to retinal degeneration. "We focused on validation of EFEMP1 expression in the cochlea because a gene encoding an effector of EGF-mediated cell signaling causes progressive hearing loss, and single mutations in the EFEMP1 gene cause two inherited forms of macular degeneration." (PMID 31185063, 2019).
male infertility (1 paper, 2021). The inability of the male to effect fertilization of an ovum after a specified period of unprotected intercourse.
medullary thyroid cancer (1 paper, 2023). "Epithelial lung, pancreatic, colorectal, head and neck, and medullary thyroid cancer all have a subset of patients whose cancers are driven by dysregulation of epidermal growth factor (EGF) secretion and/or overexpression/mutation of epidermal growth factor receptor (EGFR)." (PMID 37754956, 2023).
Merkel cell carcinoma (1 paper, 2018). "Basic fibroblast growth factor (bFGF), transforming growth factor-p1 (TGFp1), nerve growth factor (NGF), and epidermal growth factor (EGF) did not affect proliferation of Merkel cell carcinoma cells." (PMID 30895270, 2018).
mesenchymal neoplasms (1 paper, 2011). "This scenario represents a novel role for EGF as a regulator of Fas-induced cell death in mesenchymal neoplasms." (PMID 22135505, 2011). "This scenario therefore represents a novel role for EGF and CTGF as regulators of Fas-induced cell death in mesenchymal neoplasms." (PMID 22135505, 2011).
middle ear cholesteatoma (1 paper, 2021). "In addition, none of the clinical studies described any cases of middle ear cholesteatoma after topical application of FGF2 or EGF." (PMID 34306094, 2021).
mucinous adenocarcinoma (1 paper, 2018). An invasive adenocarcinoma composed of malignant glandular cells which contain intracytoplasmic mucin. "HB tumors were predominantly non-mucinous adenocarcinomas and showed overexpression of a subset of genes typical of surface colonocytes and EGF signaling." (PMID 30563495, 2018).
mucinous cystadenocarcinoma (1 paper, 2017). An invasive adenocarcinoma characterized by cystic changes and the presence of malignant glandular cells which contain intracytoplasmic mucin. "For instance, a recent study showed that EGF induced downregulation of CLDN3 in mucinous cystadenocarcinoma via the MEK/ERK or PI3K/Akt signaling pathway by inducing degradation of the TJ proteins with changes in structures and functions." (PMID 28160565, 2017).
muscle degeneration (1 paper, 2026). "Consequently, this study examinates the alteration of the EGF signalling in DMD and provides new molecular interactions in muscle that can be useful for targeted therapies of muscle degeneration." (PMID 41513629, 2026).
myelofibrosis (1 paper, 2025). A partial or complete replacement of the bone marrow stroma by fibrous tissue. "Cytokines associated with the progression of myelofibrosis encompass transforming growth factor-β, epidermal growth factor, platelet-derived growth factor, basic fibroblast growth factor, and calmodulin." (PMID 40421095, 2025).
myelosuppression (1 paper, 2021). Myelosuppression or bone marrow suppression is a condition in which bone marrow activity is decreased, resulting in fewer red blood cells, white blood cells, and platelets. "In this study, we used EGF as a positive therapeutic agent because it has been proved that systemic administration of EGF accelerated the recovery of LT-HSCs and improved the survival of mice after radiation-induced myelosuppression." (PMID 32749649, 2021).
myocarditis (1 paper, 2022). Myocarditis is a condition that is characterized by inflammation of the heart muscle (myocardium). "The first patient enrolled incurred an event of grade 3 myocarditis (LVEF 25%–30%) on cycle 1 day 8 and was determined to be related to nivolumab and unrelated to CIMAvax-EGF." (PMID 35992783, 2022).
myoma (1 paper, 2017). "Thus, high levels of estrogen, as well as, growth factors, such as insulin-like growth factor (IGF) and epidermal growth factor (EGF), may promote growth of myoma, thus current drinkers may be at increased risk." (PMID 29176884, 2017).
myxoma (1 paper, 2024). A benign soft tissue neoplasm characterized by the presence of spindle and stellate cells, lobulated growth pattern, and myxoid stroma formation. "The communication between macrophages and myxoma cells involved several signaling pathways reported to promote macrophage M2-like polarization, such as ANGPT, ANNEXI, ANXA1, VISFATI, and GAS signaling pathways 53,54and tumor growth-promoting pathways, such as EGF and PDGF signaling pathways 55,56." (PMID 39090109, 2024).
neck cancer (1 paper, 2015). "A separate pool of cells isolated from the head-and-neck cancer biopsy were stimulated with a growth factor cocktail of EGF/ HGF/IGF1 and demonstrated response along pAKT, pERK and pSTAT5 pathways." (PMID 25807104, 2015).
Neisseria gonorrhoeae infection (1 paper, 2011). "Neisseria gonorrhoeae infection induces expression, processing and release of amphiregulin, an epidermal growth factor (EGF) family member that is anti-apoptotic." (PMID 21998584, 2011).
oropharyngeal cancer (1 paper, 2020). Carcinoma, predominantly squamous cell, arising from the epithelial cells of the oropharynx. "Another type of cancer in which p16 plays a role is oropharyngeal cancer; indeed, it has been found to be a prognostic factor associated with a better outcome and a decreased epidermal growth factor (EGFR) expression." (PMID 32945604, 2020).
osteomyelitis (1 paper, 2025). An acute or chronic inflammation of the bone and its structures due to infection with pyogenic bacteria. "In a RCT that assessed the use of recombinant human epidermal growth factor versus SOC in a similar patient population with osteomyelitis, 52.1% of DFUs in the SOC group healed at 52‐weeks." (PMID 41346156, 2025).
ovarian serous cystadenocarcinoma (1 paper, 2013). A malignant serous cystic epithelial neoplasm arising from the ovary. "Additionally, in ovarian serous cystadenocarcinoma cell lines, EGF was found to downregulate the cytotoxic effects of CPE via claudin-4." (PMID 23685873, 2013). "EGF was found to downregulate claudin-3 in mucinous ovarian carcinoma cell lines and claudin-4 in ovarian serous cystadenocarcinoma by inducing the degradation of these proteins with also changes in the structure and function of TJ via the MEK/ERK or PI3K/AKT signaling pathway." (PMID 23685873, 2013).
paraplegia (1 paper, 2012). Complete paralysis of the lower half of the body including both legs, often caused by damage to the spinal cord. "In the present study, dMSCs and SKPs were isolated simultaneously from the same back skin sample from patients with paraplegia when SKP proliferation medium (DMEM/F12 containing 40 ng/ml FGF2 and 20 ng/ml EGF) was used during the initial stage." (PMID 23226248, 2012).